IL4 (interleukin 4)
Diseases named in the same sentence as IL4 in open-access papers (continued):
Sharing a sentence is not in itself a finding about the gene and the disease.
Sepsis (161 papers, 2008 to 2025). Sepsis is defined as life-threatening organ dysfunction caused by a dysregulated host response to infection. "After excluding sepsis and engraftment syndrome cases, the IL-2/IL-4 ratio on day +7 remained associated with aGVHD." (PMID 40718494, 2025). "IL-4 and other cytokines were found associated with sepsis severity, organ failure and death in a cohort of patients with septic shock." (PMID 38143267, 2023). "Facilitates IL-4-associated M2-type differentiation of macrophages and decreased clinical scores of sepsis, inhibiting mortality in septic mice." (PMID 34956210, 2021). "In contrast, the Th type 2 (Th2) responses (secrete IL-4, IL-5, IL-13 and IL-10) were elevated, leading to a suppressed adaptive immune response and increased susceptibility to sepsis." (PMID 34209240, 2021). "We have found an association between the IL-4 (−1098 T/G) polymorphism and susceptibility for sepsis and outcomes." (PMID 26561011, 2015). "At (−1098 T/G) position of the IL-4 gene, we observed that patients having GG genotypes had significantly (p = 0.009, OR (95 %) =11, CI = 1.8-66.9) higher risk to develop sepsis complications as compared to other two genotypes (TT and TG)." (PMID 26561011, 2015). "In this study, by using deficient mice, we found that the antiinflammatory cytokine IL-4 has a relevant influence on GBS-induced sepsis and septic arthritis." (PMID 19606256, 2009). "The diagnostic and prognostic roles of IL-4 in human sepsis have been poorly investigated to date." (PMID 41301767, 2025). "Anti-inflammatory IL-10 cytokine signaling pathway was over-represented, which is a well characterized mediator of immunosuppression in severe sepsis, and IL-4/IL-13 pathways associated with M2 (and reprogrammed) macrophages that have been associated with sepsis." (PMID 37304268, 2023). "Similarly, in humans, mRNA expression of IL-4 was associated with survival of patients with severe sepsis." (PMID 25614712, 2014). "It was recently suggested that polymorphisms in the IL-4 gene promoters may affect the balance of Th1 and Th2 response and, consequently, predispose trauma patients to develop sepsis." (PMID 25614712, 2014). "Interestingly, IL-4 functions as a Th2 cytokine, and elevated expression of IL-4 has been linked to reduced inflammation during sepsis in humans." (PMID 22241984, 2011). "In the examination of cytokine levels in the serum and lung homogenate of sepsis mice, quantitative detection results revealed potential challenges associated with utilizing downstream molecules, particularly critical anti-inflammatory cytokines, such as IL-4, IL-10, etc.." (PMID 38255822, 2024). "The release of IL-4 and IL-10 in sepsis suppress Th1 inflammatory response by reducing IFN-γ, TNF-α and IL-1β secretion by Th1 cells and inhibit Th1 cells polarization." (PMID 40364841, 2025). "Higher IL-4 levels in 10 P-SIRS patients suggest that they were either in an advanced SIRS stage or transitioning toward sepsis." (PMID 40584120, 2025). "Mechanistically, during the late immunosuppressive phase of sepsis, M2 macrophages are activated by Th2 cytokines (IL-4 and IL-13), LPS, glucocorticoids, IL-10, IL-6, or TGF-β." (PMID 40364841, 2025). "Our results suggested IL-4 levels and the IL-2/IL-4 ratio on day +7 were higher in patients with sepsis than those in the control group; however, the difference was not significant." (PMID 40718494, 2025). "In more advanced stages, exosomes also carry anti-inflammatory cytokines (IL-4, IL-10), reflecting the biphasic nature of the immune response in sepsis." (PMID 41268545, 2025). "The most prominent cytokines in sepsis related immunosuppressive were IL-4, IL-10, IL-27, IL-37, IL-38 and TGF-β." (PMID 40364841, 2025). "Compared with the SIRS cohort, Sepsis_D patients exhibited higher levels of Calprotectin (p = 0.0072), Azurocidin (p < 0.0001), IL-4 (p = 0.0112), IL-8 (p = 0.0015), IL-10 (p = 0.0007), TNF-α (p = 0.0198), and IL-35 (p < 0.0001)." (PMID 41301767, 2025).
Sepsis (continued). "Our data showed that IL-4 levels were significantly higher in Sepsis_D patients compared with healthy controls and SIRS, whereas differences among controls, SIRS, and Sepsis_A patients were not statistically significant." (PMID 41301767, 2025). "In contrast, during the late stage of sepsis, M2-like macrophages can be activated by Th2 cytokines (IL-4 and IL-13), TGF-β, IL-10, glucocorticoids, and immune complexes." (PMID 39252831, 2024). "The study further demonstrated that IL-4 nanotherapy resolved immunoparalysis in mice with lipopolysaccharide-induced hyperinflammation, as well as in ex vivo human sepsis models and in experimental endotoxemia." (PMID 39060761, 2024). "Inflammatory factors such as AXIN-1, FGF-19, FGF-23, IL-4, and OSM were negatively causally associated with sepsis, while IL-2 was positively associated." (PMID 39205680, 2024). "A recent study used nanomedicine to target interleukin-4 (IL-4) to myeloid cells to alleviate sepsis-induced immunoparalysis, utilizing the principles of trained immunity." (PMID 39060761, 2024). "In sepsis, an elevation in the secretion of IL-4 occurs, which consequently transfers undifferentiated T cells into Th2 cells." (PMID 39267971, 2024). "WT B6 mice were intraperitoneally injected with α-GalCer or OCH (an IL4-biased α-GalCer analog) one week prior to the induction of sepsis." (PMID 39355237, 2024). "In sepsis, the amount of IL-4 derived from Th2 is more, and the balance between Th1 and Th2 is imbalanced, presenting an immunosuppressive state." (PMID 39252831, 2024). "In our study, we identified several inflammatory factors, including FGF-19, AXIN1, FGF-23, IL-4, OSM, and IL-2, that showed statistically significant associations with sepsis risk using the IVW method in MR analyses." (PMID 39205680, 2024). "The JAK/STAT pathway is a prominent signaling cascade activated by several critical cytokines implicated in sepsis, such as IFN-γ, IL-4, IL-6, IL-10, and IL-12." (PMID 39062636, 2024). "And apoA1–I L4, a fusion protein of apolipoprotein A1 (apoA1) and IL4, was developed to resolve sepsis-induced immune-paralysis." (PMID 39267971, 2024). "Significantly higher levels of serum IL-6 (404.54 ± 543.38 vs 185.11 ± 242.73 pg/ml), IL-2 (5.30 ± 2.03 vs 4.11 ± 1.67 pg/ml), and IL-4 (4.76 ± 1.31 vs 3.34 ± 1.37 pg/ml) were found in patients with KD combined with severe sepsis (all P<0.05, respectively)." (PMID 37234775, 2023). "We subsequently demonstrate that IL4 nanotherapy resolved immunoparalysis in mice with lipopolysaccharide-induced hyperinflammation, as well as in ex vivo human sepsis models and in experimental endotoxemia." (PMID 37291433, 2023). "APOE increased the levels of Th1 cytokines in the serum and decreased the production of IL‐4 in sepsis, which is the main Th2 cytokine produced by Natural killer T cells." (PMID 37026377, 2023). "S100A8/9, IL-1, IL-4, and tumor necrosis factor have all been identified in previous research as markers of sepsis-related brain damage in plasma." (PMID 37901226, 2023). "IL-4 is a major factor in B cell activation and differentiation and it plays an important role in the pathogenesis of sepsis and inflammation." (PMID 38143267, 2023). "A nanoparticle integrating a fusion protein of apolipoprotein A1 and interleukin-4 and that targets myeloid-cell-rich haematopoietic organs resolves immunoparalysis in ex vivo and in vivo models of sepsis." (PMID 37291433, 2023). "HIF-1α was shown to be a critical determinant of sepsis promoting the production of inflammatory cytokines, including TNF-α, IL-1, IL-4, IL-6, and IL-12, which reach harmful levels during early sepsis." (PMID 35682644, 2022). "For the anti-inflammatory cytokines (IL-4, IL-5, IL-10, IL-13), only the concentrations of IL-1RA showed a significant difference between children with sepsis compared to children with either clinical malaria or febrile controls." (PMID 35811678, 2022).
Sepsis (continued). "ELISA results showed that the levels of inflammatory factors in the burn sepsis group were significantly higher than those in the other two groups and that IL-4, IL-6, and TNF-α continuously increased over time." (PMID 35280898, 2022). "MiR-223 was found to alleviate sepsis by binding to the mRNA of NFAT5 and Rasa1 and causing IL-4-meditated M2 macrophage differentiation." (PMID 34956210, 2021). "In inbred C57BL/6 mice, IL-4 was shown to be a driving force of septic arthritis and sepsis by significantly impairing the capability of the host to clear the bacteria." (PMID 33546401, 2021). "In our study, sham and CLP mice secreted similar amounts of IL-4, but ATRvD1 was able to reduce its mRNA expression in sepsis-surviving mice." (PMID 34769064, 2021). "In the regulation of cytokine production, some cytokines had been proved to be beneficial for the control of sepsis, such as the anti-inflammatory cytokines of IL-1Ra, IL-4, IL-6, IL-10, IL-11, IL-13, IL-35, and TGF-β." (PMID 34938184, 2021). "Of note, injection of miR-223-overexpressed macrophages that were pretreated with IL-4, alleviated sepsis symptoms in the LPS model." (PMID 34956210, 2021). "Upregulation of mir-223 impelled M2 macrophage through lower activity of glycolysis Pathway. theImplementation ofmiR-223 over-expressed macrophages with IL-4 pre-conditioning alleviated sepsis severity." (PMID 34956235, 2021). "• Does the activity of IL-1RA, IL-4, IL-10, and/or TGF-β contribute to sepsis-associated immunosuppression?" (PMID 32676795, 2020). "A number of anti-inflammatory cytokines are upregulated during the course of sepsis (e.g., IL-1RA, IL-4, IL-10, and TGF-β)." (PMID 32676795, 2020). "Consistent with sepsis pathology, anti-inflammatory cytokines, IL-4 and IL-10, contained in exosomes of sepsis mice increased in the late phase." (PMID 33013905, 2020). "The levels of anti-inflammatory cytokines (IL-4 and IL-10) in plasma were found to be increased in the narciclasine treatment group compared to the untreated sepsis group." (PMID 32076015, 2020). "The administration of miR-223 over-expressed macrophages, with IL-4 preconditioning, attenuated sepsis severity in LPS model." (PMID 32658933, 2020). "In our results, the cytokine profiles of the lung environment showed an increase of Ccl2 and Il4 transcripts, 10 days after sepsis." (PMID 32425929, 2020). "The administration of IL-4 stimulated miR-223 over-expressed macrophages attenuated the severity of LPS injection sepsis mouse model." (PMID 32658933, 2020). "Significant differences were observed in the expression of the pro-inflammatory cytokine genes IL-2, IL-6, TNF, and IFN-γ and the anti-inflammatory cytokine genes IL-4 and IL-10 between sepsis patients and healthy controls." (PMID 32922168, 2020). "Meanwhile, the differentiation of T lymphocytes was dysregulated under sepsis exposure as shown by the polarization of Th2 cells due to the decreased expression of IFN-γ but enhanced production of IL-4, indicating the outward signs of immunosuppression." (PMID 30881224, 2019). "In a previous network analysis, the IL-4 gene was the hub node among the sepsis group, implying that this gene was related with other cytokine molecules." (PMID 31583025, 2019). "To characterize the type 2 cytokines secreted from lung ILC2 following sepsis, we measured IL-4, IL-9, and IL-13 expression in the ILC2 increased in the lungs by flow cytometry." (PMID 29511181, 2018). "Our findings also demonstrate that CD43 drives a TH1 phenotype, as CD43-/- demonstrate significantly decreased IL-2+ CXCR3+ CD4+ (TH1-like) cells with a concomitant increase in IL-4+ CCR4+ CD4+ (TH2-like) cells in sepsis." (PMID 30226896, 2018). "During sepsis, the levels of IFNγ, IL-6, IL-10, and IL-4 were significantly elevated in the moderate preterm group only." (PMID 30555806, 2018). "Animals were treated with anti-IL-4 as described in Materials and Methods on days 0, 2, 4, and 6 post sepsis and monitored for survival." (PMID 30226896, 2018).
Sepsis (continued). "IL-4 is a well-known predominant cytokine of Th2 cell (immune cell of adaptive immunity) with a lesser influence in innate immune response in sepsis." (PMID 30119646, 2018). "Our data show association between serum levels of the cytokines IL-4, IL-6, IL-10 and TNF, and cognitive performance of patients with severe sepsis or septic shock." (PMID 29540719, 2018). "Anti-inflammatory interleukins (IL-4, IL-5, IL-10) were significantly lower in sepsis patients and close to the lowest detection limit of the assays." (PMID 29379043, 2018). "IL4 was up regulated in the melioidosis patients, including the diabetic cohort, compared to other sepsis cases." (PMID 28628607, 2017). "IL-4&GM-CSF-differentiated MO obtained from mice surviving sepsis had significantly lower expression of CD1a and CD83, two exclusive markers for monocyte-derived immature and mature cells, respectively." (PMID 28507543, 2017). "Collectively, these data indicate that IL-33/ST2 and IL-4/IL-13/STAT6 signalling are required for the expansion of Treg cells in sepsis-surviving mice, linking IL-10-secreting M2 macrophage in this process." (PMID 28374774, 2017). "The levels of C-RP, SC5b-9 (innate immune response mediators), and IL-10 or IL-4 (anti-inflammatory cytokines) were elevated during sepsis in both groups." (PMID 27293317, 2016). "On univariate logistic regression analysis, the distribution of genotypes at positions IL-1α (−889 C/T), IL-4 (−1098 T/G), IL-10 (−1082 A/G), allele A of TNF-α (−238) and allele T of IL-10 (−889) were significantly (p < 0.05) predominant in sepsis." (PMID 26561011, 2015). "Theoretically, proinflammatory cytokines (IL-6 and TNF-α) and anti-inflammatory cytokines (IL-4 and IL-10) are increased during sepsis even if IL-4 is often found at low levels probably owing to its short half-life in plasma (5–19 minutes)." (PMID 26635427, 2015). "Nor was there supernatant evidence that interphase neutrophils from sepsis patients produced cytokines (IL-2, IL-4, IL-6, IL-10, TNF or IFNγ) when cultured in vitro (unstimulated total cells or enriched CD66b + interphase neutrophils)." (PMID 25084831, 2014). "In murine models of graft arterial disease and sepsis, CD80 is associated with proinflammatory cytokine stimulation, while CD86 plays a protective role mediated through IL-4 or IL-10 production." (PMID 24472094, 2014). "For instance, C5aR mRNA expression was greatly reduced in monocytes and monocyte-derived dendritic cells by Th2 cytokine IL-4, which was significantly up-regulated during sepsis." (PMID 23233853, 2012). "Overall these findings are consistent with prior observations that over-expression of IL-4 improves survival in mice with sepsis and Pseudomonas pneumonia." (PMID 22110673, 2011). "As anti-inflammatory cytokines can also play a role in the response to severe sepsis we next looked at the levels of IL-10, IL-4, IL-11 and IL-5." (PMID 21124895, 2010). "The later phase of sepsis, characterized by the generation of immunosuppressive cytokines such as IL-10 and IL-4 is often referred to as compensatory anti-inflammatory response syndrome." (PMID 19442306, 2009). "This eosinophil production was enhanced by IL-4 and IL-5, and suggests a T-helper lymphocyte type 2 cytokine activation in response to sepsis after traumatic injury." (PMID 18435836, 2008). "For example, interleukin (IL)-1, IL-6, IL-12, interferon (IFN)-γ, macrophage migration inhibitory factor (MIF), IL-10, transforming growth factor (TGF)-β, and IL-4 attempt to restore the immunological equilibrium and balance the pro- and anti-inflammatory cascades during sepsis." (PMID 40142568, 2025). "Recent literature has highlighted the often-contradictory role of IL-4 in sepsis." (PMID 41301767, 2025). "On the other hand, anti-inflammatory cytokines, like IL-4 and IL-10, attempt to counterbalance the excessive inflammatory response but may contribute to immunosuppression in sepsis." (PMID 39205680, 2024).
Sepsis (continued). "The negative association of 5-hydroxyindole sulfate with sepsis, and its association with increased IL-4 (which is negatively associated with sepsis), suggests that IL-4 is not a mediator for 5-hydroxyindole sulfate’s protective effect against sepsis." (PMID 39205680, 2024). "Our results showed that correlates promoting the development of infectious complications in patients with sepsis-associated ARDS included SOFA score, oxygenation index, the application of vasoactive drugs, NLR, IL-4, and IL-17A, in addition to CD16brightCD62Ldim neutrophils and IL-8." (PMID 38605959, 2024). "Anti-inflammatory cytokines, IL-4 and IL-10, play crucial roles in maintaining the balance of the inflammatory response and preventing tissue damage and organ failure due to excessive inflammation during sepsis." (PMID 39502702, 2024). "We identified 36 metabolites significantly associated with sepsis (p < 0.05), with AXIN1, FGF-19, FGF-23, IL-4, and OSM showing an inverse association, suggesting a protective role, while IL-2 exhibited a positive correlation, indicating a potential risk factor." (PMID 39205680, 2024). "In addition, the discharge of anti-inflammatory cytokines IL-4 or IL-10 can control the progression of sepsis." (PMID 36914568, 2023). "In addition, IL-4 promoted lung epithelial cell regeneration in sepsis-induced acute lung injury by polarizing macrophages to the M2 type." (PMID 38037190, 2023). "Finally, we studied the therapeutic potential of the IL4 nanoparticles in multiple translational inflammation and in vivo and ex vivo models of sepsis." (PMID 37291433, 2023). "Stimulation of IL-4 and IL-13 in vitro after sepsis increases microglial mitochondrial content with its function enhanced, drives restorative microglia (M2-like) transition and inhibits the release of inflammatory cytokines to confer neuronal protective effects." (PMID 36445634, 2023). "The use of IL-4 or gadolinium chloride to inhibit the effect of proinflammatory microglia (M1-like) can lead to a decrease in the number of microglia, inhibiting the production of cytokines and preventing oxidative stress during sepsis." (PMID 36445634, 2023). "Moreover, the mRNA expression level of the anti-inflammatory cytokine IL-4, which can control the progression of sepsis, in kidneys of atp1Δ/Δ-infected mice was significantly higher than that in the kidneys of WT-infected mice and NS-control mice (P < 0.001)." (PMID 36914568, 2023). "Moreover, it was found that administration of miR-223 over-expressed macrophages, with IL-4 preconditioning, attenuated sepsis severity in a LPS model, through the inhibition of the glycolysis pathway." (PMID 35911719, 2022). "Also, significantly lower levels of IL-4 (p<0.0001), IL-10 (p<0.0001), and IL-13 (p<0.05) were measured/detected in children with sepsis compared to children with clinical malaria." (PMID 35811678, 2022). "In addition, the immunosuppressive effect of sepsis is augmented by release of IL-4 and IL-10, both of which were shown to reduce expression of pro-inflammatory cytokines." (PMID 35879778, 2022). "Sepsis-related anti-inflammatory cytokines mainly include IL-4, IL-10, and IL-37." (PMID 36209190, 2022). "In sepsis, the release of IL-4 is increased, leading to the differentiation of naive T cells into Th2 cells, and the maturation of Th2 cells can be blocked by anti-IL-4 antibodies." (PMID 36209190, 2022). "Indeed, miR-223 was a critical factor in regulating IL-4-induced M2 differentiation of macrophages by controlling Nfat5 and Rasa1 protein production, thus modulating the pathophysiology of sepsis." (PMID 34956210, 2021). "However, in another inbred strain, 129SV mice, the opposite was true, i.e., IL-4 protected the mice from S. aureus induced sepsis." (PMID 33546401, 2021). "Notably, LPS increased neutrophil expression of CD274 (PD-L1), which is consistent with other stimulants of sepsis, such as IL-1β, HMGβ1, G-CSF and IL-4." (PMID 33549126, 2021).